MMP8 (matrix metallopeptidase 8)
Diseases named in the same sentence as MMP8 in open-access papers (continued):
Sharing a sentence is not in itself a finding about the gene and the disease.
ischemic stroke (7 papers, 2019 to 2024). A stroke disorder caused by obstruction of blood flow to the brain, due to thrombotic (local blood clot formation) or embolic (due to a blood clot or other material traveling from another site) event. "The second Mendelian study focused on the association between MMP-8 levels and ischemic stroke and its subtypes, finding that higher serum levels of MMP-8 were associated with increased risks of small vessel stroke." (PMID 38697862, 2024). "When wGRS used one MMP gene at a time, only MMP8 significantly associated with the increased risk of ischemic stroke (adjusted-OR = 2.74, 95% CI = 1.21–6.17)." (PMID 31752174, 2019). "When wGRS used one MMP gene at a time, only MMP-8 gene significantly associated with the increased risk of ischemic stroke (adjusted-OR = 2.74, 95% CI = 1.21–6.17)." (PMID 31752174, 2019). "In our study, the wGRS summarizing the influence of MMP-7, MMP-8 and MMP-26 was associated with ischemic stroke." (PMID 31752174, 2019). "Although the results from our study need to be replicated in other studies, our data suggest that a cumulative effect of genetic variants from MMP-7, MMP-8 and MMP-26 on the risk of ischemic stroke." (PMID 31752174, 2019). "In summary, we found that a wGRS that includes variants of MMP-7, MMP-8 and MMP-26 was associated with increased risk of ischemic stroke." (PMID 31752174, 2019). "The first study examined the causal effects of MMP-1, MMP-8, and MMP-12 levels on ischemic stroke." (PMID 38697862, 2024). "It found that lower serum levels of MMP-12 were associated with an increased risk of ischemic stroke, lower serum levels of MMP-1 and MMP-12 were linked to an increased risk of large-artery stroke, and higher serum levels of MMP-8 were associated with an increased risk of small vessel stroke." (PMID 38697862, 2024). "As MMP-8 was shown to play beneficial roles during the healing process, further studies should assess the long-term effects of neutrophil inhibition in the context of ischemic stroke." (PMID 32977685, 2020). "There was a significant interaction between high genetic and high modifiable CVD risk, indicating that the combined genetic risks from MMP-7, MMP-8 and MMP-26 may modify the association of high modifiable CVD risk with ischemic stroke." (PMID 31752174, 2019). "Additionally, MMP8 rs3740938, rs1940475, rs11225395 and MMP26 rs2499966 were associated with ischemic stroke in recessive models." (PMID 31752174, 2019). "Surprisingly, salivary matrix metalloproteinase-8 (MMP-8), MPO, and IL-1 levels, as well as the MMP-8/TIMP-1 ratio, were significantly lower in patients with ischemic stroke." (PMID 33897941, 2021).
acute coronary syndrome (6 papers, 2013 to 2022). Signs and symptoms related to acute ischemia of the myocardium secondary to coronary artery disease. "high serum concentrations of MMP-8 and MMP-8/TIMP1 ratios were strongly associated with acute coronary syndrome." (PMID 23365489, 2013). "High MMP-8 and tissue-inhibitor of matrix metalloproteinase-1 (TIMP-1) levels are implicated in acute coronary syndrome (ACS)." (PMID 28278213, 2017). "But more accurately, they demonstrated that the robust staining for MMP-8 and M∅ was localized to the lesion's shoulder, a region prone to rupture, and provokes acute coronary syndromes." (PMID 23365489, 2013). "The plasma levels of MMP8 and MMP9 have also been shown to increase in AAD compared to healthy controls and to selected patients with acute coronary syndromes." (PMID 23442769, 2013).
Aortic dissection (6 papers, 2013 to 2022). Aortic dissection refers to a tear in the intimal layer of the aorta causing a separation between the intima and the medial layers of the aorta. "In addition, a combined use of MMP8 and DD has been proposed in ruling out aortic dissection in the diagnostic workup: as a matter of fact, the application of low cutoffs for both biomarkers was proven to be highly sensitive, and it allowed safe dissection’s being ruled out in 20% of patients." (PMID 35892496, 2022). "A number of circulating biomarkers have been suggested to be useful, alone or in combination, essentially in ruling out aortic dissection (DD, MMP8, smMHC, sELAF, PC1)." (PMID 35892496, 2022). "In addition, CRP levels positively correlate with DD levels in aortic dissection, suggesting the presence of a strict relationship between these two factors in the pathophysiology of the complication and with plasma MMP8 and MMP9 in patients suspected of dissection." (PMID 35892496, 2022). "It has been reported that when aortic dissection occurs, the serum levels of MMP1, MMP2, MMP3, MMP8, and MMP13 are increased, and the expression of MMP9 in the cytoplasm of smooth muscle cells in the aortic wall is enhanced." (PMID 35463768, 2022). "Preliminary studies have detected increased plasma levels of MMP8 and MMP9 in patients with acute aortic dissection (AAD)." (PMID 23442769, 2013). "Among these, a low cutoff for plasma MMP8 has been correlated with ideal sensitivity and a negative predictive value for aortic dissection, suggesting a potential role in ruling out the occurrence of the disease." (PMID 35892496, 2022). "Plasma levels of MMP8 and MMP9 in acute aortic dissection versus alternative diagnoses." (PMID 23442769, 2013). "Low levels of plasma MMP8 can rule out acute aortic dissection in a minority of patients." (PMID 23642232, 2013).
fibrosis (6 papers, 2010 to 2022). the formation of excess fibrous connective tissue in an organ or tissue in a reparative or reactive process. "To study the implication of MMP-8 in the pathogenesis of bleomycin-induced fibrosis we measured its level in lung homogenates." (PMID 20949050, 2010). "In fibrosis mice, consistently, the expression of genes related to ECM accumulation (TIMP1, MMP3 and MMP8) were decreased and genes involved in ECM elimination (MMP2, MMP9 and MMP13) were notably upregulated after JT003 treatment." (PMID 33199780, 2020). "However, there is minimal or no staining for MMP-8 in areas of mild fibrosis in IPF lung and in rejected normal lung transplant donor lungs." (PMID 24828408, 2014).
head and neck cancer (6 papers, 2014 to 2024). A primary or metastatic malignant neoplasm affecting the head and neck. "Few reports have indicated the possibility of using MMP-8 to predict survival in patients with colorectal or head and neck cancer." (PMID 39682156, 2024). "Univariate Cox proportional hazards regression demonstrated a significant correlation between MMP25 (HR=0.81, p = 0.04) and MMP8 (HR=1.26, p = 0.05) and prognosis of head and neck cancer patients." (PMID 32850314, 2020). "Previous studies of head and neck cancers have discovered that MMP-9 plasma concentrations correlate with disease stages of the cancer and MMP-8 plasma levels correlate with T-status, N-status and disease staging." (PMID 25423087, 2014).
oral cancer (6 papers, 2012 to 2025). "Further, it has been shown that higher MMP8 levels correlate to lower risk of distant metastasis, as well as better prognosis of patients with breast or oral cancer." (PMID 27292876, 2016). "MMP-7 is mainly expressed in the invasive portion of oral cancer, whereas MMP-8 and MMP-9 are mainly detected in peritumoral inflammatory cells." (PMID 36275775, 2022). "For example, MMP8 expression has been demonstrated as a favorable prognostic factor of patients with breast or oral cancer." (PMID 27292876, 2016). "In addition, MMP8 downregulation in non-metastatic cells increases their metastatic potential, and high MMP8 levels in human carcinomas correlate with lower metastasis incidence and a better prognosis to patients with breast or oral cancer." (PMID 22822400, 2012).
tongue cancer (6 papers, 2008 to 2024). A malignant neoplasm affecting the tongue. "A study reported that an elevated MMP-8 expression in tongue carcinoma cells was associated with an increased survival." (PMID 26155333, 2015). "By contrast, parallel analysis with MMP-8 revealed that production of this protease was significantly associated with good clinical outcome in tongue cancer patients." (PMID 18253113, 2008). "Furthermore, and by using mice deficient in this metalloproteinase and oral carcinoma cells producing MMP-8, we examine putative molecular and cellular mechanisms underlying the protective effect of this enzyme in tongue cancer." (PMID 18253113, 2008). "Previous studies report tumour-suppressive effects of MMP8 in breast, skin and tongue cancers and include various mechanisms affecting tumourigenesis, migration, invasion and metastasis." (PMID 34059618, 2021). "Here we found that in tongue cancer cells, cell-matrix adhesion was unaffected by MMP8, but instead, enhanced cell-to-cell adhesion was observed, indicating molecular mechanisms different from that reported for the other cancers." (PMID 34059618, 2021). "Here, we used the N-terminomics/TAILS to characterize and identify novel MMP8 substrates in tongue cancer cells." (PMID 34059618, 2021). "In tongue cancer, we have previously shown similar effects of MMP8 on carcinoma cell behaviour in vitro and in vivo." (PMID 34059618, 2021). "Consistently, oestrogen-induced MMP-8 expression in cultured HSC-3 tongue carcinoma cells, and MMP-8 cleaved oestrogen receptor (ER) α and β." (PMID 18253113, 2008). "Molecular forms of MMP-8 were identified from HSC-3 tongue carcinoma cells by using western blotting which demonstrated a 75 kDa species in HSC-3 cell membrane extracts." (PMID 18253113, 2008). "There was a strong statistical support to the observation that the MMP-8 KO female mice developed tongue cancer more often than the wild-type mice." (PMID 18253113, 2008). "MMP-8 expression was further analysed in cultured oral SCC cells by confocal immunofluorescence, which localised MMP-8 immunoreactivity mainly to the tongue carcinoma cell membranes and to subcellular granules." (PMID 18253113, 2008). "siFXYD5 diminished the viability and motility of HSC-3 cells independent of MMP8 and similar effects were seen in another tongue cancer cell line, SCC-25." (PMID 34059618, 2021). "Half (6/12) of the MMP-8 KO female mice in contrast to none of the 12 wild-type C57BL/6 female mice developed tongue cancer during the experiment." (PMID 18253113, 2008).
aneurysm (5 papers, 2012 to 2024). Bulging or ballooning in an area of an artery secondary to arterial wall weakening. "Patients with BAV and aneurysms ≥55 mm in diameter had considerably higher levels of MMP-8 and MMP-9 in the convex sites than in the concave sites." (PMID 22645456, 2012). "Higher MMP-8 and MMP-9 levels were detected in the convex aortic sites than in the concave aortic sites of BAV patients with aneurysms ≤54 mm in diameter." (PMID 22645456, 2012).
bladder cancer (5 papers, 2019 to 2022). "High mRNA level of MMP8 has been reported in bladder cancer and is positively correlated with tumor grade." (PMID 32922663, 2020). "In silico analysis indicated that MMP-8 expression was elevated in bladder cancer tissue compared to that in the control." (PMID 31638929, 2019). "Results from the TCGA database, containing 408 primary tumor and 19 normal samples, revealed that MMP-8 expression was elevated in bladder cancer tissue as compared to their control counterpart (P < 0.01)." (PMID 31638929, 2019). "Results from in silico analysis showed that MMP-8 expression was elevated in bladder cancer tissue as compared to the control counterpart." (PMID 31638929, 2019). "Furthermore, we investigated whether the MMP-8 expression had an effect on the overall survival time of bladder carcinoma participants." (PMID 31638929, 2019). "Treatment of bladder cancer with bacterial CBM588 strongly inhibited the tumor growth in vivo in mice, which was suggested to be due to the release of TNF-related apoptosis-inducing ligand (TRAIL) from PMN cells by MMP8." (PMID 31514474, 2019). "In some cancer cell lines, no MMP8 mRNA was detected, such as in bladder cancer, Ewing’s sarcoma, chondrosarcoma or follicular thyroid carcinoma cells, and thus, the mechanistic role of MMP8 in those cancers has not been examined." (PMID 31514474, 2019).
chronic obstructive pulmonary disease (5 papers, 2016 to 2023). A chronic and progressive lung disorder characterized by the loss of elasticity of the bronchial tree and the air sacs, destruction of the air sacs wall, thickening of the bronchial wall, and mucous accumulation in the bronchial tree. "MMP-8 and IL-18 are pro-inflammatory markers associated with chronic obstructive pulmonary disease (COPD)." (PMID 34127548, 2021). "MMP-8 can degrade basement membrane and extracellular proteins, causing airway disruption and remodeling in chronic obstructive pulmonary disease (COPD)." (PMID 33119648, 2020).
heart failure (5 papers, 2013 to 2022). Inability of the heart to pump blood at an adequate rate to meet tissue metabolic requirements. "Because LV remodeling is associated with increased risk of death an heart failure in post-MI, we investigated the associations of MMPs and TIMPs to cardiovascular outcome and found that baseline levels of MMP-8 predicted prognosis after MI." (PMID 23967183, 2013). "While LVEF was not directly assessed, MMP-8 levels were also independently associated with the development of cardiovascular death and hospitalisation for heart failure, indicating a link between increased MMP-8 levels and LV dysfunction." (PMID 35896723, 2022). "Finally, higher levels of MMP-8 and -9 were observed in patients who experienced heart failure during hospitalization and in patients with lower LVEF." (PMID 23967183, 2013). "By univariate analysis, there were positive relations between cardiovascular death or hospitalization for heart failure during the 3-year follow-up and the baseline levels of MMP-2 (P = 0.03), MMP-8 (P = 0.002), and MMP-9 (P = 0.03)." (PMID 23967183, 2013). "Considering TTC biopsy data and the previous findings in heart-failure patients, we suggest that the severity of TTC may be affected by fibrosis due to low MMP-8 and high TIMP-1 levels." (PMID 28278213, 2017).
osteosarcoma (5 papers, 2017 to 2022). A usually aggressive malignant bone-forming mesenchymal neoplasm, predominantly affecting adolescents and young adults. "In osteosarcoma cells, the overexpression of this miRNA led to reduced proliferation, invasion and migration, suggesting MMP8 acts as a tumor-promoting factor in osteosarcoma." (PMID 31514474, 2019). "In jaw cysts, MMP8 was only detected in plasma cells, and in osteosarcoma it was detected in about 50% of biopsy and resection samples but not at all in metastases." (PMID 31514474, 2019). "In osteosarcoma, MMP8 is negatively regulated by microRNA-539 through a special binding site in the MMP8 3′-UTR, which may inhibit osteosarcoma cell proliferation and migration." (PMID 28423488, 2017). "And previous literature has reported that miR-539 can suppress osteosarcoma cell invision and migration in vitro by targeting Matrix metallopeptidase-8.These investigations indicated that miR-539 may play a pivotal role in various human tumours, including osterosarcoma." (PMID 33879126, 2021). "For example, it has been reported that miR-2682-3p could inhibit osteosarcoma cell proliferation by targeting CCND2 (Cyclin D2), MMP8 (Matrix metallopeptidase 8), and Myd88 (Myeloid differentiation primary response gene 88)." (PMID 35733138, 2022). "Both MMP8 and MMP9 were produced by osteoclasts in osteosarcoma tissue." (PMID 34811438, 2021).
prostate carcinoma (5 papers, 2018 to 2026). A carcinoma that arises from epithelial cells of the prostate gland. "MMP8 is also unique and interesting as a putative metastasis suppressor, yet the role of MMP8 in prostate cancer metastasis in bone remain to be fully elucidated." (PMID 36054271, 2023). "Salivary MMP‐8 levels were found to be higher in prostate cancer patients undergoing ADT compared to healthy individuals." (PMID 35769040, 2022). "The concentration of salivary MMP‐8 levels was higher in prostate cancer patients undergoing ADT compared to healthy individuals." (PMID 35769040, 2022). "Our study is the first study, to the best of our knowledge, in which the concentration of salivary MMP‐8 level was analyzed in prostate cancer patients undergoing ADT." (PMID 35769040, 2022). "High MMP8 expression, measured only from circulating tumor cells, in the blood of metastatic castration-resistant prostate cancer patients correlated with lower overall survival." (PMID 31514474, 2019). "Across all three lytic‐like human prostate cancer cell lines, BMP inhibition resulted in decreased MMP8 and increased BMP3 gene expression." (PMID 36054271, 2023). "MMP8 transcription was also found to be regulated and lost upon BMP inhibition in lytic‐like prostate cancer cells, suggesting that lytic‐like cells may use MMP8 to facilitate the destruction of bone with matrix degradation." (PMID 36054271, 2023). "These include MMP8, a metallopeptidase that contributes to extracellular matrix remodeling, NAALAD2, a peptidase that hydrolyses N-acetyl-aspartyl glutamate and glutamate and a marker of prostatic carcinomas, and ACVRL1, a receptor for TGF-β family of ligands." (PMID 29608722, 2018). "Interestingly, in prostate cancer cells, no MMP8 was detected even after induction with CCL25." (PMID 31514474, 2019).
squamous cell carcinoma of the tongue (5 papers, 2008 to 2022). "According to these data, we propose that, contrary to the role of most proteases produced by human carcinomas, MMP-8 has a protective, probably oestrogen-related role in the growth of mobile tongue SCCs." (PMID 18253113, 2008).
acute kidney injury (4 papers, 2013 to 2022). Sudden and sustained deterioration of the kidney function characterized by decreased glomerular filtration rate, increased serum creatinine or oliguria. "Similar results were found among patients with Acute Kidney Injury (AKI) where the overexpression of genes such as MMP8, IL1R2, and OLFM4 was associated with increased severity and organ failure." (PMID 33692779, 2021). "Recently, Basu and collaborators demonstrated a persistent histopathologic and functional injury and worsened health in MMP8-null mice subjected to acute kidney injury (AKI) suggesting MMP8 expression and activity seems to be directly proportional with recovery." (PMID 33275619, 2020). "The concentrations of E-cadherin increased proportionately to the renal failure progression, whereas EMMPRIN and MMP-8 values could not differentiate between CKD stages 3–4 and CKD stage 5." (PMID 23054081, 2013).